PIAS3 (protein inhibitor of activated STAT 3)
Diseases named in the same sentence as PIAS3 in open-access papers (continued):
Sharing a sentence is not in itself a finding about the gene and the disease.
liver fibrosis (1 paper, 2024). "Deficiencies in STAT3 DNA-binding were reported to be mediated by increasing the expression of Pias3 in liver fibrosis." (PMID 38751599, 2024).
lymphoma (1 paper, 2016). A malignant (clonal) proliferation of B- lymphocytes or T- lymphocytes which involves the lymph nodes, bone marrow and/or extranodal sites. "The PIAS3 transcript is rarely detected in certain cancers such as mesotheliomas and lymphoma cells, and loss of PIAS3 expression is responsible for constitutive STAT3 activation." (PMID 26768588, 2016).
malignant mesothelioma (1 paper, 2018). A malignant neoplasm of the pleura or peritoneum, arising from mesothelial cells. "We previously reported that in malignant mesothelioma (MM), low PIAS3 expression is associated with increased STAT3 activation and correlates with poor patient survival, yet the regulatory mechanism(s) governing PIAS3 expression in MM remain unclear." (PMID 30259640, 2018). "Our previous findings have shown that PIAS3 expression is downregulated in lung squamous cell cancer and malignant mesothelioma (MM)." (PMID 30259640, 2018).
nodular medulloblastomas (1 paper, 2016). "In the case of PIAS3, significant differences of nuclear PIAS3 detection were evidenced between the tumor-surrounding brain tissues (58.8%; 10/17) and the classical (21.3%; 13/61; p = 0.000), the large-cell (15.9%; 7/44; p = 0.000) or the nodular medulloblastomas (6.70%; 1/15; p = 0.000)." (PMID 28035977, 2016).
Obesity (1 paper, 2024). Accumulation of substantial excess body fat. "Furthermore, our investigation uncovered distinct protein expression patterns in obesity-related EC which includes elevated levels of oncogenic proteins such as TMEM205, STAT5, FAS and identified downregulation of tumor suppressor protein PIAS3." (PMID 39414985, 2024).
pancreatic cancer (1 paper, 2015). "Finally, our data suggests that Cav-1 depletion in pancreatic cancer cells affects various pathways, particularly the JAK/STAT pathway, by decreasing activation of JAK2 and STAT3 and by increasing SOCS2, PIAS3, and DUSP5 inhibitory signals." (PMID 26065715, 2015).
renal cell carcinoma (1 paper, 2020). "We can see that SENP5, SENP3, UBE2I, PIAS3, TRIM27, SAE1, and CBX4 are risk factors in the development of renal cell carcinoma." (PMID 33123273, 2020).
small cell lung carcinoma (1 paper, 2021). Small cell lung cancer (SCLC) is a highly aggressive malignant neoplasm, accounting for 10-15% of lung cancer cases, characterized byrapid growth, and early metastasis. "In addition, there were 6 common KEGG pathways in the CIN-CC group (p < 0.01), namely, the adipocytokine signaling pathway, small cell lung cancer (ITGA6, PIAS3, and LAMC2), pathways in cancer, the Toll-like receptor signaling pathway, graft versus host disease, and the TGF-beta signaling pathway." (PMID 34174849, 2021).
spondylitis (1 paper, 2019). The inflammation of a vertebra. "Although spondylitis was not completely prevented by PIAS3 in mice with SpA, it could effectively reduce molecules involved in inflammation and osteoproliferation of the spine in mice with SpA." (PMID 30630513, 2019).
squamous cell tumors (1 paper, 2015). "Thus, we hypothesize that SCC inhibition may be achieved clinically by reversing the PIAS3 deficiency present in a subgroup of squamous cell tumors, restoring its inhibition of STAT3-mediated cell proliferation." (PMID 25573684, 2015).
viral infection (1 paper, 2025). "Therefore, downregulation of PIAS3 may relieve normal inhibition present in the absence of viral infection, thus contributing to the expression of interferon and ISGs." (PMID 41165334, 2025).
tumor (46 papers, 2013 to 2026). "Consistently, in the MKN45 cell‐derived xenograft model, METTL10‐induced tumor progression was partially alleviated by the PIAS3‐K442A mutation." (PMID 41114928, 2025). "In addition, some studies suggest that inactivation of PIAS3 may be involved in tumor-associated immunosuppression via IDO expression in chemoresistant cancers." (PMID 27148255, 2016). "Our studies indicated higher levels of PIAS3 mRNA in normal and tumor tissues and significantly lower levels in mastopathy." (PMID 40003884, 2025). "Our findings indicated that PIP and STAT5 levels decrease with a higher tumor grade, size, and tumor/nodes/metastasis (TNM) clinical stage, while nuclear PIAS3 levels increase with tumor progression." (PMID 40003884, 2025). "By analyzing the expression of PIAS family members in human tumor tissues, we found that PIAS3 mRNA and protein expression were more intense in tumor tissues compared to adjacent normal tissues." (PMID 38528630, 2024). "Normal ovarian and endometrial cells showed increased expression of PIAS3, while in tumor cells, the expression was considerably decreased." (PMID 38590645, 2024). "Brassinin (BSN), a phytoalexin, first isolated from cabbage, has anti‐tumor effects via enhancing PIAS3 expression." (PMID 38590645, 2024). "We also found that the PIAS3 protein is more strongly expressed in tumor tissues by analyzing the actual protein expression in human tumor tissues." (PMID 38528630, 2024). "Another protein family member Smurf E3 ubiquitin–protein ligase catalytic domain interacts with the PY motif of Smad6 and facilitates PIAS3 degradation in order to promote tumor growth, invasion, and survival." (PMID 38590645, 2024). "miR-181b activates STAT3, promoting the Warburg effect in CRC cells and CRC xenograft growth in mice, and does that by inhibiting PIAS3 expression, as the Warburg effect and tumor growth are reversed with PIAS3 overexpression." (PMID 35887358, 2022). "Recently, the PAI‐1/PIAS3/Stat3/miR‐34a axis has been reported to regulate tumour metastasis in NSCLC." (PMID 33932101, 2021). "miR-9 and miR-181a activated the JAK/STAT signaling pathway via targeting SOCS3 and PIAS3 respectively, resulted in T-cell immunity inhibition and tumor progress." (PMID 34707990, 2021). "Intracolonic administration of PIAS3 lentivirus or anti-miR-18a lentivirus in AOM/DSS-induced mice led to dramatically reduced tumor sizes/numbers, whereas knockdown of PIAS3 in CAC mice significantly promoted tumor growth." (PMID 33921348, 2021). "Studies have shown that miR-18a and miR-19a contribute to tumour metastasis by targeting the negative regulators of Wnt/β-catenin signalling, such as PIAS3 and MXD135,36." (PMID 31186404, 2019). "All this evidence suggests that PIAS3 plays an important role as a tumor suppressor in many cancers." (PMID 30259640, 2018). "The resveratrol-treated tumour tissues showed less Ki67 labelling, widely distributed apoptotic regions, upregulated PIAS3 expression and reduced p-STAT3 nuclear translocation." (PMID 30176837, 2018). "The level of the STAT3 signalling inhibitor PIAS3 was increased in resveratrol-treated tumours of the LP group." (PMID 30176837, 2018). "The PIAS3 anti-invasive effect is also consistent with translational findings suggesting that expression of PIAS3 correlates with reduced metastasis of multiple tumor types." (PMID 30096838, 2018). "Previously, we have shown that PIAS3 is a tumor suppressor in MM cells and that low PIAS3 protein expression predicted poor survival in MM patients." (PMID 30259640, 2018). "Our findings indicate that the pathway of miR-199a-5p targeting both PIAS3 and p27 is a possible mechanism that contributes to tumour growth in OS." (PMID 28120918, 2017). "Patients with decreased PIAS3 expression in tumor tissues tended to have advanced tumor stage and positive node metastasis." (PMID 26768588, 2016).
tumor (continued). "As a positive control, we used the same two cell lines, NL-20 and A549, as used previously to examine tumor PIAS3 expression." (PMID 25573684, 2015). "We demonstrate for the first time that PIAS3 expression is low to negligible in a majority of SCC tumor specimens by western blotting." (PMID 25573684, 2015). "When normalized to actin, PIAS3 expression level in the squamous tumor samples was consistently lower compared to NL-20, except for one tumor sample, and even more distant from the A549 PIAS3 expression level." (PMID 25573684, 2015). "From these results, we chose the Calu-1 cell line as our model system because its low PIAS3 expression best reflected the pattern observed in the human tumor specimens." (PMID 25573684, 2015). "The aim of the present study was to evaluate the relationship between STAT5A/B, COX-2, and PIAS3 mRNA expression and tumor staging, metastasis status, and histopathological subtype in 71 patients with confirmed non-small cell lung cancer (NSCLC) diagnosis." (PMID 25137041, 2014). "While PIAS3 suppressed expression, supporting the idea that colony-initiated signaling pathways are activated early in carcinogenesis, suggesting that colony dysregulation and its signaling pathways precede changes in conventional tumor markers." (PMID 40520790, 2025). "However, the PIAS3 (nuclear) level significantly increased with tumor histology grade (G1: 0.26 ± 0.44, G2: 0.45 ± 0.49, G3: 0.68 ± 0.46, p < 0.001; G1 vs. G2: p < 0.01, G1 vs. G3: p < 0.001, G2 vs. G3: p < 0.001)." (PMID 40003884, 2025). "By contrast, the expression levels of nuclear PIAS3 tended to increase as the tumor progressed." (PMID 40003884, 2025). "Further investigation indicated that CASC2, as a tumor suppressor lncRNA, could directly regulate PIAS3 expression by acting as a ceRNA for miR-18a, leading to STAT3 inactivation and inhibiting in vitro and in vivo CRC tumor growth." (PMID 38185635, 2024). "Of interest, PIAS3 can bind NF-κB promoting its SUMOylation and inhibiting its activity, potentially targeting the expression of many pro-inflammatory genes required for tumor progression." (PMID 31557897, 2019). "A previous study by our laboratory showed that as a tumor suppressor, low PIAS3 expression predicts poor patient survival in MM, yet the mechanism(s) regulating PIAS3 expression in MM still remain unclear." (PMID 30259640, 2018). "Furthermore, we found the tumour volume in the as‐miR‐181b + PIAS3 siR group was larger than that in the as‐miR‐181b + Scr siR group." (PMID 30054984, 2018). "We and others have also reported that restoring PIAS3 expression by curcumin and other natural compounds, such as ascochlorin and brassinin, have anti‐tumor effects, indicating that PIAS3 restoration can be a potential therapeutic strategy for cancer treatment." (PMID 30259640, 2018). "Moreover, PIAS3 functioned to negatively regulate cell growth and tumor sphere formation in GBM cells, indicating that PIAS3 loss in GBM contributes to enhanced STAT3 activity and subsequent cell proliferation." (PMID 29950561, 2018). "Thus, by promoting STAT3 activation, repression of PIAS3 expression in tumor cells can indirectly contribute to NK cell dysfunction by altering the cytokine profile of the cancer." (PMID 27148255, 2016). "Indeed, the large majority of human tumor samples showed minimal expression of PIAS3 when compared to a normal lung epithelial cell line (NL-20) and an adenocarcinoma cell line (A549)." (PMID 25573684, 2015). "Furthermore, combination with BSN and paclitaxel led to an increased expression of PIAS-3 in the tumor tissues." (PMID 25788267, 2015). "Consistently, the expression of PIAS3 was significantly low in TRAMP-C1 siAR tumours, confirming that PIAS3 is an AR downstream target, and the PIAS3 down-regulation by AR silencing could be an important step for STAT3 activation in PCa cells." (PMID 23982944, 2013).
tumor (continued). "PIAS3 is an endogenous inhibitor of STAT3 through prohibiting its DNA binding, and the loss of PIAS3 in cancers contributes to enhanced STAT3 activity and subsequent tumor growth, as well as impacts patient survival, identifying PIAS3 a promising therapeutic target." (PMID 29950561, 2018). "Furthermore, the promotive effect of miR‐181b on the Warburg effect and tumour growth could be reversed by PIAS3 knockdown." (PMID 30054984, 2018). "In addition to miR-199a-5p in OS, other miRNAs that could target PIAS3 in tumours have been reported." (PMID 28120918, 2017). "On the basis of the inverse correlation between the expression of miR-199a-5p and the protein levels of PIAS3 and p27 in OS patient tissues and other evidence, we considered that the pathway of miR-199a-5p targeting both PIAS3 and p27 is a possible mechanism that contributes to tumour growth in OS." (PMID 28120918, 2017). "Additionally, a miR-199a-5p-targeted inhibitor could significantly enhance PIAS3 and p27 expression and ultimately suppress the tumour growth in a xenograft model of OS, which represents a potential therapeutic approach that may be valuable for OS therapy." (PMID 28120918, 2017). "Thus, the targeting of STAT3 by PIAS3 as a mechanism for tumor inhibition may represent a promising treatment in SCC." (PMID 25573684, 2015). "Tumor-derived exosomes with miR-9 and miR-181a activated JAK/STAT by targeting SOCS3 and PIAS3 to promote MDSCs expansion." (PMID 40443670, 2025). "Using RT-PCR, the expression levels of PIP, PIAS3, SOCS3, STAT5A, and STAT5B were verified at the level of mRNA isolated from the tumor’s margin (normal) (n = 40), mastopathy (n = 16), and BC tumor tissue (n = 42)." (PMID 40003884, 2025). "The present study showed that PIAS3, an upstream inhibitor of the STAT3 signaling pathway, is one of the mechanisms by which HUC-MSCs supernatants inhibit tumor cells." (PMID 37057281, 2023). "Taken together, Res inhibited STAT3 signaling through modulation of PIAS3, SHP1, SHP2, and SOCS3, thereby attenuating tumor growth and increasing sensitivity to TMZ." (PMID 37298405, 2023). "It has been shown that ectopic expression of PIAS3 in cancer cells can suppress the transcriptional activity of STAT3 and inhibit tumour growth." (PMID 30054984, 2018). "Moreover, after treatment with the miR-199a-5p AMO, the levels of miR-199a-5p, KI-67 and PCNA significantly declined, while the protein levels of p27 and PIAS3 significantly increased, suggesting that an inhibitor targeting miR-199a-5p could remarkably suppress tumour growth in OS." (PMID 28120918, 2017). "We suggest that BSN inhibits STAT3 signaling through modulation of PIAS-3 and SOCS-3, thereby attenuating tumor growth and increasing sensitivity to paclitaxel." (PMID 25788267, 2015). "In lymphocytic leukemia, various aberrant signaling pathways in tumor microenvironment, including ZAP-70 protein, MAPK, and STAT3, stimulate the expression of post-translational regulator microRNA (miR-21) and other tumor suppressor genes (PTEN, PDCD4, and PIAS3)." (PMID 38590645, 2024). "PIAS3 is upregulated to inactivate STAT3, promoting apoptosis and autophagy in tumor cells." (PMID 37057281, 2023). "Res and TMZ exert the anti-tumor effects mainly by inhibiting STAT3 signaling, and inhibition of STAT3 signaling might be related to upregulation of PIAS3, SHP1, SHP2, and SOCS3." (PMID 37298405, 2023). "The tumour tissues in the combination treatment group showed growth inhibition, extensive apoptosis, suppressed STAT3 expression and nuclear translocation and upregulated PIAS3 expression." (PMID 30176837, 2018). "The negative correlation between STAT5B and PIAS3 (rho = −0.43) was also observed in T2a+T2b tumor group." (PMID 25137041, 2014).
tumor (continued). "Another recent study has shown that the exosome-derived micro-RNA miR-181a is able to inhibit PIAS3, resulting in activation of the JAK/STAT signaling pathway that promotes the development of early-stage myeloid-derived suppressor cells, thereby accelerating tumor growth and immune escape." (PMID 35887358, 2022). "Oxidative stress is involved in tumor development, and in HepG2 cells, it has been shown that exposure to H2O2 decreases PIAS3 expression while increasing STAT3 expression and that overexpression of PIAS3 recovers the anti-oxidative response, decreases cell migration and invasion capacity." (PMID 35887358, 2022). "Additionally, statistically significant negative correlation between STAT5B and PIAS3 genes was observed in T2a+T2b tumor group (rho = −0.43, P = 0.041; Spearman's rank correlation)." (PMID 25137041, 2014). "In the same tumor group, the negative correlation between STAT5B and PIAS3 expression was statistically significant." (PMID 25137041, 2014). "DIM treatment could not affect the miR-21 level and protein levels of PTEN, PIAS3 and p-STAT3 in the splenic MDSCs from miR-21−/− tumor-bearing mice." (PMID 35773674, 2022). "However, tumor-suppressive roles of SOCS3 and PIAS3 have not yet been established." (PMID 27167343, 2016).